GSK3B (glycogen synthase kinase 3 beta)
Diseases named in the same sentence as GSK3B in open-access papers (continued):
Sharing a sentence is not in itself a finding about the gene and the disease.
intracerebral hemorrhage (9 papers, 2016 to 2026). A cerebrovascular disorder characterized by bleeding into one or both cerebral hemispheres including the basal ganglia and the cerebral cortex. "Our study demonstrates that salvianolic acid A improves ferroptosis in rats with intracerebral hemorrhage by promoting NRF2 activation via Akt /GSK-3β." (PMID 38816543, 2024). "Similarly, regulatory T cells (Tregs) have been reported to alleviate inflammatory injury after intracerebral hemorrhage by shifting the microglia/macrophage polarization toward the M2 phenotype via the IL-10/GSK3B/PTEN axis." (PMID 41476593, 2025). "Moreover, a recent study showed that the PI3K/Akt/GSK3β signaling pathway plays a vital role in neuroprotection after intracerebral hemorrhage." (PMID 32082121, 2019).
medulloblastoma (9 papers, 2014 to 2024). A malignant, invasive embryonal neoplasm arising from the cerebellum. "Firstly using AKT inhibitors in our PI3K-activated models, we confirmed the AKT/GSK3β cilia disassembly pathway that we previously proposed in Inpp5e-null medulloblastoma cells." (PMID 39168978, 2024). "Given that Paullones, including alsterpaullone, have been identified as CDK1/CDK2/CDK5 and GSK3B inhibitors, we examined the gene expression profiles of the CDK genes in the Group 3 medulloblastoma cell lines." (PMID 26061748, 2015). "LiCl (a GSK-3β inhibitor) notably decreased cell proliferation in cerebellar GNPs in Math1::SmoM2 Fi/+ neoplastic cells and in neoplastic cells from ptc+/− mice (another SHH medulloblastoma model)." (PMID 34577571, 2021). "Lithium, which is a GSK3β inhibitor, effectively decreases cell proliferation and induces nonapoptotic cell death in Wnt subtype medulloblastoma, in which Wnt signaling is up-regulated by accumulation of intracellular β-catenin." (PMID 26504084, 2015).
Nephropathy (9 papers, 2016 to 2025). A nonspecific term referring to disease or damage of the kidneys. "Previous studies showed that p-GSK3β and p-Tau were concurrently increased accompanying renal dysfunction and nephropathy after adriamycin injury." (PMID 35368760, 2022). "To observe the effect of inhibiting GSK3β on METH-induced nephropathy, we tested the podocyte specific protein level after LiCl (GSK3β inhibitor) treatment." (PMID 35368760, 2022). "Based on the results that luteolin could prevent METH-induced GSK3β activation, Tau phosphorylation, and nephropathy, we hypothesize that inhibiting GSK3β activation could also alleviate nephropathy." (PMID 35368760, 2022). "Inhibiting Tau phosphorylation by blocking Tau kinase GSK3β could alleviate METH-induced nephropathies." (PMID 35368760, 2022). "Accumulating data also indicate that LiCl could diminish p-Tau level through GSK3β, resulting in podocyte pathology amelioration in adriamycin-induced nephropathy." (PMID 35368760, 2022). "Inhibiting GSK3β activation using LiCl could reverse p-Tau upregulation and related nephropathies." (PMID 35368760, 2022). "To verify this hypothesis, we used LiCl to inhibit GSK3β directly and demonstrated the protective benefit of LiCl on METH-induced nephropathy." (PMID 35368760, 2022). "Moreover, the activity of GSK3β was augmented in other CKDs, such as focal segmental glomerular sclerosis (FSGS), folic acid (FA) nephropathy, and chromic allograft nephropathy." (PMID 36225562, 2022).
alopecia (8 papers, 2019 to 2025). Hair loss usually from the scalp. "The effects of GSk3β inhibition on hair growth are also known to be associated with the development of alopecia." (PMID 36362835, 2022). "Moreover, DHT was revealed to cause alopecia via suppression of the Wnt/β-catenin signaling pathway by activating GSK-3β, and PTGDS is induced by the androgen receptor (AR)." (PMID 36831222, 2023). "Western blotting analysis demonstrated that in the model group, sodium hydrosulfide‐induced alopecia led to significant downregulation of Wnt10b and β‐catenin, and upregulation of GSK‐3β." (PMID 40678337, 2025). "We ranked targets from high to low based on degree and used the average degree as a threshold to obtain 124 targets that were considered the most critical targets for TGD treatment of alopecia, including GSK3β." (PMID 36588691, 2022). "TGF-β1, VEGF, PI3K, AKT, and GSK-3β have been reported to be involved in the occurrence and development of alopecia." (PMID 36440360, 2022). "Our results confirmed that TJFs enhance HDP cell proliferation via the Akt/ERK/GSK-3β signaling pathway, suggesting a potential treatment for alopecia." (PMID 31088549, 2019). "Our results confirmed that ELF-EMFs enhance hDPC activation and proliferation via the GSK-3β/ERK/Akt signaling pathway, suggesting a potential treatment strategy for alopecia." (PMID 31991762, 2020). "We also found that DHT-induced alopecia was alleviated by treatment with KY19382, a small molecule mimetic of PTD-DBM which induces hair growth by simultaneous inhibition of the functions of CXXC5 and GSK-3β." (PMID 36831222, 2023).
Arthritis (8 papers, 2009 to 2024). Inflammation of a joint. "Our findings indicated that AB treatment relieves arthritis pain by inhibiting GSK‐3β activation, increasing antioxidant capability, reducing Drp1‐mediated mitochondrial dysfunction and suppressing neuroinflammation." (PMID 38334255, 2024). "In summary, TDZD-8 treatment inhibits GSK-3β activity, reduces mitochondrial mediated oxidative stress, suppresses spinal inflammasome response, and alleviates arthritis pain." (PMID 37058473, 2023). "In our study, we found that AB4 treatment alleviated arthritis pain by inhibiting GSK‐3β activity." (PMID 38334255, 2024). "GSK-3β participates arthritis pain via modulating mitochondrial mediated oxidative stress." (PMID 37058473, 2023). "Indeed inhibition of GSK3β or ablation of the GSK3β gene ameliorates inflammation dependent arthritis." (PMID 19274078, 2009). "AB4 treatment inhibits spinal GSK‐3β activity, enhances Nrf2/GPX4 antioxidant response, reduces Drp1‐mediated mitochondrial ROS production, suppresses NLRP3 inflammasome activation and alleviates arthritis pain." (PMID 38334255, 2024). "GSK-3β inhibitor TDZD-8 treatment suppresses spinal Bax and DHODH mediated mitochondrial ROS levels, inhibits NF-κB mediated NLRP3 inflammation activation, and alleviates arthritis pain." (PMID 37058473, 2023).
cerebral infarction (8 papers, 2018 to 2025). An ischemic condition of the brain, producing a persistent focal neurological deficit in the area of distribution of the cerebral arteries. "Wnt-3a protein administration leads to Gsk3b dephosphorylation, reducing cerebral infarction and neuronal apoptosis through the Foxm1 pathway." (PMID 40529227, 2025). "Whether liraglutide could suppress the activation of GSK-3β by modulating the APP metabolism to hinder Aβ generation in the regions away from the primary lesion after cerebral infarction needs further elucidation." (PMID 30618584, 2018). "In addition, Ang II increased the area of cerebral infarction, promoted neuronal degeneration and apoptosis, aggravated neurological deficits on righting and geotaxis reflexes, and was accompanied by increased expressions of phosphorylated GSK-3β and mTOR." (PMID 33425219, 2020).
colorectal tumor (8 papers, 2014 to 2023). "The activation of GSK3β in colorectal tumors in mice treated with SP contributes to decreased β-catenin expression and to reduced tumor growth as assessed by enhanced apoptosis and reduced [18F]-FDG uptake measured by PET/CT." (PMID 36998441, 2023). "Consistently, the expression of NLRP12 was significantly reduced, while p-GSK3β and β-catenin were upregulated in mouse and human colorectal tumor tissues." (PMID 37581937, 2023). "The expression of GSK-3β was elevated in colorectal tumor tissue in comparison to adjacent normal tissue almost in all patients both KRAS mutant and wild-type." (PMID 34955846, 2021). "DADS was reported to prevent the development of colorectal tumor by blocking inflammation, a process largely involving GSK-3β suppression and the inhibition of NF-κB nuclear translocation." (PMID 32377166, 2020). "Our results suggest that targeting GSK-3β may be of benefit for the therapeutic activity of anticancer drugs against colorectal tumor." (PMID 25002914, 2014).
cyst (8 papers, 2014 to 2025). A sac-like closed membranous structure that may be empty or contain fluid or amorphous material. "β-catenin downregulation may be associated with the observed GSK3β upregulation and subsequent cyst development." (PMID 25799508, 2015). "These lithium-induced microcysts are GSK3-positive with enhanced inhibitory phosphorylation of GSK3β at serine 9, and the cyst epithelium is proliferative." (PMID 40526103, 2025). "Collecting ducts are central to cyst formation, and GSK3β inhibition has been shown to reduce cyst formation and renal cyst hyperplasia." (PMID 40526103, 2025). "OPN contains an RGD domain that binds αV‐integrins, which are key mediators of mitogenic signals (such as GSK3β and mTOR) and macrophage recruitment that contribute to cyst growth." (PMID 39238069, 2024). "Finally, to determine the function of GSK-3β during germline cyst breakdown and primordial follicle formation, 17.5 dpc ovaries were cultured with BIO for 4 days (equaling 2 dpp)." (PMID 30866939, 2019). "While GSK3β’s role in later-stage PKD, particularly in cyst expansion and fibrosis, is well-documented, its involvement in the early stages of the disease remains less clear." (PMID 40526103, 2025). "Glycogen synthase kinase‐3β (GSK‐3β) is a known target of lithium, and lithium‐induced microcysts are GSK‐3β positive and the cyst epithelium is proliferative." (PMID 24744881, 2014). "Here we show that dysregulation of the GSK3β/β-catenin, but not mTOR/S6 pathway is another crucial player for Dicer-dependent cyst development." (PMID 25799508, 2015). "In chronic lithium‐treated adolescent rats, COX‐2 is not colocalized with microcystic epithelium, mitotic activity, and inactive pGSK‐3β in collecting duct; a blocker of COX‐2 does not prevent cell proliferation, cyst formation, or GSK‐3β inactivation." (PMID 24744881, 2014). "Moreover, GSK-3β has a novel functional role in polycystic kidney disease (PKD) pathophysiology, and its inhibition may be therapeutically useful to slow down cyst expansion and progression of PKD." (PMID 33897769, 2021).
dyslipidemia (8 papers, 2012 to 2025). "HFD‐induced metabolic syndrome in rats is mediated by activating GSK3β which reduce insulin sensitivity, and using of GSK3β inhibitor lithium can reverse these metabolic alterations." (PMID 39644152, 2024).
frontotemporal dementia (8 papers, 2008 to 2025). Frontotemporal dementia (FTD) comprises a group of neurodegenerative disorders, characterized by progressive changes in behavior, executive dysfunction and language impairment, as a result of degeneration of the medial prefrontal and frontoinsular cortices. "In frontotemporal dementia (FTD), hyperphosphorylated tau driven by CDK5 and GSK3β causes microtubule destabilization and neurofibrillary pathology." (PMID 41303499, 2025).
head and neck squamous cell carcinoma (8 papers, 2012 to 2026). A squamous cell carcinoma that arises from any of the following anatomic sites: lip and oral cavity, nasal cavity, paranasal sinuses, pharynx, larynx, and salivary glands. "The results showed that the mRNA and protein expression of GSK3B, PIK3CA, FN1, MET, and SPP1 was significantly upregulated in head and neck squamous cell carcinoma tissues, while MAPK3 was significantly downregulated." (PMID 39323640, 2024). "In head and neck squamous cell carcinoma (HNSCC), downregulation of PFN2 reduced phosphorylation/expression of AKT, GSK-3β, and β-catenin, leading to reduced invasion and metastasis." (PMID 33171868, 2020).
influenza (8 papers, 2013 to 2020). An acute viral infection of the respiratory tract, occurring in isolated cases, in epidemics, or in pandemics; it is caused by serologically different strains of viruses (influenzaviruses) designated A, B, and C, has a 3-day incubation period, and usually lasts for 3 to 10 days. "Even though most pathways were activated in most treatments, “Granzyme B Signaling” in the first age transition, and “Role of Wnt/GSK-3β Signaling in the Pathogenesis of Influenza” in the second transition, were both suppressed under all exposure scenarios." (PMID 32015368, 2020). "In switchers, the most enriched pathways included those involved in regulation of epithelial mesenchymal transition pathway, basal cell carcinoma signaling, as well as Wnt/GSK-3β signaling in the pathogenesis of influenza." (PMID 33391847, 2020). "“Wnt/β-catenin signaling”, “PCP pathway” and “Role of Wnt/GSK-3β signaling in the pathogenesis of influenza” are all changed in mHtt mice (repression) but in opposite direction when Pin1 is depleted (activation)." (PMID 27199664, 2016). "Loss of Pin1 in HdhQ111 mice was able to counteract changes in “Wnt/β-catenin signaling”, “PCP pathway” and “Role of Wnt/GSK-3β signaling in the pathogenesis of influenza” as triggered by mHtt." (PMID 27199664, 2016). "Wnt/GSK-3β signaling that plays a role in the pathogenesis of influenza was also modulated." (PMID 27200301, 2016).
Myotonia (8 papers, 2015 to 2025). An involuntary and painless delay in the relaxation of skeletal muscle following contraction or electrical stimulation. "In fact, it was shown that GSK3β inhibition improved defects in myotonia, myogenesis, and muscle strength in a DM1 mouse model." (PMID 36767649, 2023). "Moreover, GSK3β inhibition led to an overall enhancement in muscle fatigue resistance and mass recovery, improved muscle strength and reduced myotonia in different types of murine models of muscle wasting diseases, indicating that GSK3β has a crucial role in muscle regeneration." (PMID 36795689, 2023). "The treatment of mice with the GSK3β inhibitors, lithium and 4-benzyl-2-methyl-1,2,4-thiadiazolidine-3,5-dione (TDZD-8), restored the balance of cyclin D3-CELF1 and reversed myotonia and muscle strength in treated HSALR mice, showing promise for targeting GSK3β as a muscle therapy for DM1." (PMID 35563013, 2022). "Thus, the correction of GSK3β-CUGBP1 signaling in DM1 mouse models recovers not only muscle dysfunction (muscle weakness, myotonia, atrophy and myopathy), but might also reduce CNS pathology." (PMID 37445828, 2023).
ovarian tumors (8 papers, 2011 to 2025). "Many upstream proteins of c-Myc are found overexpressed in ovarian tumors, one of which is glycogen synthase kinase 3β (GSK-3β)." (PMID 34065149, 2021). "It was also found that β-arrestin acts as an ETAR signal transducer by inactivating GSK-3β through the PI3K/ILK/AKT pathway, thereby promoting WNT signaling and contributing to the chemoresistance, invasion, and metastasis of ovarian tumors." (PMID 28439256, 2017). "Because endothelial cells generally enhance ovarian cancer cell survival, previous attempts to target ovarian tumors included the use of an ETR agonist (Atrasentan, ABT-627) to inhibit cell proliferation and VEGF production and to reduce ILK expression and phosphorylation of GSK-3β." (PMID 28439256, 2017).
periodontitis (8 papers, 2020 to 2026). An acute or chronic inflammatory process that affects the tissues that surround and support the teeth. "In summary, this study's results showed that LiCl significantly mitigated bone loss potentiated by Monensin in experimental periodontitis due to a strong inhibition of GSK3b." (PMID 41294202, 2025). "One of Wu Zhou’s studies found that chronic systemic exposure to Porphyromonas gingivalis lipopolysaccharide, associated with periodontitis, promotes tau hyperphosphorylation and neuroinflammation via GSK3β activation in a mouse model of AD, leading to cognitive deficits." (PMID 41406907, 2026). "In the brain of periodontitis mice, p-Akt and p-GSK3β levels were reduced, leading to tau hyperphosphorylation and neuronal loss including cell bodies and neurites." (PMID 40552124, 2025). "The prediction that multiple vitamins can interact with GSK3B underscores a shared pathway for mitigating the hyperinflammatory state that characterises progressive periodontitis." (PMID 41384443, 2025). "P-Akt and p-GSK-3β were decreased in the brains of periodontitis mice compared with the control group." (PMID 40552124, 2025). "This suggests that periodontitis may exacerbate Alzheimer's pathology, highlighting GSK3β as a potential therapeutic target to mitigate the disease's progression linked to oral health." (PMID 41406907, 2026). "We also evaluated the mRNA expression levels of several Wnt ligands and other proteins involved in β-catenin stabilization and activation, such as E-cadherin, AXIN, APC and GSK3B using a GEO database for periodontitis (GSE223924) and oral carcinogenesis (GSE85195)." (PMID 40421179, 2025). "Furthermore, glycogen synthase kinase-3 beta (GSK3B), a common hub target, is a crucial kinase that promotes NF-κB activation and the subsequent synthesis of TNF-α, IL-1β, and other mediators central to the pathogenesis of periodontitis." (PMID 41384443, 2025). "However, whether altered localization of E-cadherin, APC, GSK3B and/or AXIN proteins occur during periodontitis to drive oral carcinogenesis remains unknown." (PMID 40421179, 2025). "Additionally, transcriptional expression analysis of components of the β-catenin destruction complex during periodontitis revealed no changes in APC and GSK3B expression." (PMID 40421179, 2025). "Since the change in mRNA levels of APC, GSK3B and AXIN during periodontitis are not related to those observed during oral carcinogenesis, it seems unlikely that transcriptional regulation of components of β-catenin destruction complex would be playing a role in periodontitis and oral carcinogenesis." (PMID 40421179, 2025).
basal cell carcinoma (7 papers, 2015 to 2024). A carcinoma involving the basal cells. "The tissue samples of basal cell carcinoma showed very faint expression of both GSK3α and GSK3β (m, n), and acinic cell carcinoma showed no expression (o, p) of either GSK3α or GSK3β." (PMID 25645517, 2015).
diabetic encephalopathy (7 papers, 2020 to 2025). A brain disease that is characterized by functional impairment of cognition, cerebral signal conduction, neurotransmission and synaptic plasticity, and underlying structural pathology associated with diabetes. "In diabetic encephalopathy, decreased levels of miR-132 have been associated with the dysregulation of the GSK-3β/Tau pathway, contributing to diabetic complications." (PMID 39195481, 2024). "The repressed Akt and stimulated GSK-3β have been proven to exacerbate neuronal damage in diabetic encephalopathy." (PMID 39655056, 2024). "Combining immunofluorescence techniques and molecular analyses in vivo and in vitro, the present study provides the first time report on protective roles of miR-132 against diabetic encephalopathy injury by repressing GSK-3β expression and alleviating Tau hyperphosphorylation." (PMID 33406505, 2020).